CYP27B1 (cytochrome P450 family 27 subfamily B member 1)
Diseases named in the same sentence as CYP27B1 in open-access papers (continued):
Sharing a sentence is not in itself a finding about the gene and the disease.
rickets (continued). "It is most likely that Cyp27b1-KO rats showed more severe rickets symptoms than mutant Vdr (R270L) rats because of the absence of Vdr-independent effects of 1,25(OH)2D3." (PMID 32231239, 2020). "Finally, a third model discriminated against the SNV with the highest probability of conferring susceptibility to hypovitaminosis D of all the variants analyzed; this SNV was rs10877012 in CYP27B1." (PMID 40870018, 2025). "A total lack of VDR or CYP27B1 causes rickets but this is mainly due to its effect on intestinal calcium absorption as shown by the correction of bone and growth plate structure by a rescue diet of high calcium and lactose." (PMID 35334824, 2022). "Similarly, Vdr KO mice develop typical features of rickets, whereas Cyp27b1 KO mice suffer from severe growth retardation, hypocalcemia, and poor bone mineralization." (PMID 36009040, 2022). "Growth failure and rickets were observed in both Vdr (R270L) and Cyp27b1-KO rats." (PMID 32231239, 2020). "Administration of 25(OH)D3 reversed rickets symptoms in Cyp27b1-KO and Vdr (R270L) rats." (PMID 32231239, 2020). "As expected, targeted ablation of the CYP27B1 gene (1α-hydroxylase gene) in mice results in hypocalcemia, secondary hyperparathyroidism, retarded growth, and the skeletal abnormalities characteristic of rickets as well." (PMID 28912809, 2017). "Indeed, the infant who was diagnosed with VDDR1A at the age of one month had a low serum 1,25-OH2D and a positive CYP27B1 sequencing result but did not have any clinical or radiological signs of rickets." (PMID 30282619, 2019). "However, we also found variants in genes associated with primary hyperparathyroidism (GCM2), renal hypophosphatemia with or without rickets (SLC34A1, SLC34A3, SLC9A3R1, VDR, and CYP27B1), DiGeorge syndrome (TBX1 and NEBL), and hypophosphatasia (ALPL)." (PMID 38586466, 2024).
colon carcinoma (17 papers, 2008 to 2025). "The CYP27B1 polymorphism considerably changes alpha 1 hydroxylase enzyme activity in colon cancer cells; in addition, rs28934604, rs5891567, rs13377933, and rs2229103 decrease alpha 1 hydroxylase enzyme activity in cancer cells, while rs8176344 increases it." (PMID 41150797, 2025). "The polymorphisms in CYP24A1 and CYP27B1 were linked to prostate and colon cancer, respectively." (PMID 38672780, 2024). "Polymorphisms of CYP27B1 is responsible for progression of colon cancer, but this polymorphic gene might be responsible for growth of pituitary prolactinoma." (PMID 33709028, 2021). "After the demonstration that intestinal cells are capable of converting vitamin D into active paracrine and autocrine forms, the influence of CYP27B1 polymorphism on vitamin D has become a potential subject of research for determining the risk of colon cancer occurrence." (PMID 32260235, 2020). "The results of recent study have revealed that pro-inflammatory cytokines including IL-6 and TNF-α decreased CYP27B1 expression in colon cancer cells." (PMID 34208589, 2021). "Higher CYP27B1 expression has previously been reported in well-to-moderately differentiated states of colon cancer compared to poorly differentiated colon carcinomas." (PMID 26260259, 2015). "In colon cancer, a study using immunohistochemistry has demonstrated that CYP27B1 is present at equally high levels in normal colonic epithelium and colorectal cancer." (PMID 20831823, 2010). "Of note, CYP27B1 was abundant in Caco-2/AQ cells, as is typical for rather differentiated colon carcinomas, whereas CYP24 was overexpressed in COGA-13 cells consistent with a low degree of differentiation." (PMID 18205904, 2008). "Based on these findings and their consistency with previous ovarian and colon cancer studies, it can be concluded that CYP27B1 expression may be used as a biomarker for cancer presence and severity." (PMID 38672780, 2024). "We are the first to show in a colon cancer cell line, that TNFα inhibits CYP27B1 transcription." (PMID 24120915, 2014). "It is of note that genistein increased the expression of vitamin D hydroxylase CYP27B1 and inhibited the expression of CYP24 in colon cancer cells, although it inhibited the expression of vitamin D hydroxylase CYP24 and CYP27B1 in prostate cells." (PMID 38140273, 2023). "At the gene level, the interaction P-values of <0.05 were observed for CYP27B1 and GC (vitamin D metabolism) and IL10 (inflammation) for CRC and colon cancer." (PMID 31434255, 2019). "The inhibitory effect of TNFα on CYP27B1 and TRPV6 expression in colon cancer cells might alter calcium uptake in the inflamed intestine." (PMID 24120915, 2014). "Sub-group analysis according to gender revealed a significant difference in CYP27B1 mRNA levels between rectal and colon cancers in women (p < 0.01) but not in men (not shown)." (PMID 24213465, 2012).
Hypocalcemia (15 papers, 2013 to 2025). An abnormally decreased calcium concentration in the blood. "In Cyp27b1–/–mice, 1α,25D3 deficiency and hypocalcemia caused secondary hyperparathyroidism, with plasma PTH reaching markedly high levels." (PMID 30281599, 2018). "Cyp27b1-knockout mice (Cyp27b1–/–mice) are congenitally deficient in 1α,25D3 and exhibit marked hypocalcemia and high parathyroid hormone levels, resulting in osteodystrophy involving bone hypocalcification and growth plate cartilage hypertrophy." (PMID 30281599, 2018). "Concomitant hyperphosphatemia, reduced renal 1 alpha hydroxylase (CYP27B1) activity, and hypocalcemia (secondary to low calcitriol) are directly responsible for the increased release of PTH, leading to SHPT." (PMID 40077644, 2025). "The hypocalcemia observed in Cyp27b1–/–mice was also improved and plasma calcium was maintained at a normal level by ALF or ELD administration." (PMID 30281599, 2018). "Although a tendency for hypocalcemia was observed in Cyp27b1–/–mice treated with vehicle, the administration of ALF or ELD significantly increased plasma Ca concentration." (PMID 30281599, 2018). "In this study CYP27B1 knock out mice were fed a diet high in cholecalciferol which prevented hypocalcemia and almost rescued skeletal growth." (PMID 25329305, 2014). "Consistent with our prior studies, and despite the “rescue diet,” Cyp27b1 null females had hypocalcemia, hypophosphatemia, secondary hyperparathyroidism, lower FGF23, very low calcitriol (99.6 ± 14.1 pmol/L, above the 20 pmol/L detection limit due to fetal-placental sources), and higher 25(OH)D3." (PMID 38477809, 2024). "However, during calcium imbalance with hypocalcemia, a conversion of 25(OH)D3 to 1,25(OH)2D3—the active form vitamin D3—is markedly enhanced by 1α-hydroxylase (CYP27B1) in the renal tubular cells." (PMID 37566598, 2023). "Hypocalcemia is associated with low FGF23 levels as a study of Gcm2−/− mice characterized by hypocalcemia, hyperphosphatemia, and low calcitriol and PTH levels and Cyp27b1−/− mice with hypocalcemia, hypophosphatemia, and low 1,25(OH)2D3 but high PTH levels has revealed." (PMID 35084563, 2022). "Lowered basal levels of 1,25(OH)2D3 in M1‐IKO and M1/M21‐DIKO mice lead, in turn, to reduced intestinal absorption of Ca and P, which causes hypocalcemia and hypophosphatemia that promotes a rise in PTH and a reduction in FGF23 levels, and a broad Cyp27b1 null‐like skeletal phenotype." (PMID 33553989, 2021). "Cyp27b1–/–mice exhibit marked hypocalcemia and high PTH levels after weaning." (PMID 30281599, 2018). "Hypocalcemia, hypophosphatemia and increased PTH concentrations are known inducers of renal CYP27B1 gene expression in mice." (PMID 24019880, 2013). "Cyp27b1 null dams did have hypocalcemia, secondary hyperparathyroidism, absent calcitriol, higher 25OHD, and altered vitamin D metabolites." (PMID 38477809, 2024).
diabetes (14 papers, 2012 to 2025). "According to statistical analysis the allele G and genotype GG of the SNP CYP2R1 rs10741657 and the allele C and CC genotype of the SNP CYP27B1 rs3782130 are associated with a decreased risk of CVDs and diabetes in three of the five heritage models studied." (PMID 40237935, 2025). "The serum 25(OH)D level in patients with diabetes mellitus after long-term vitamin D3 supplementation is associated with CYP27B1 polymorphism." (PMID 31583252, 2019). "There was evidence of an association of VDBP rs4588-A with BMI (p = 0.01), CYP27B1 rs703842-G with smoking status (p = 0.02), diabetes (p = 0.01) and social class (p = 0.01) and CY27B1 rs10877012-T with smoking status (p = 0.01), and diabetes (p = 0.01)." (PMID 25488826, 2015). "As a result, the final logistic regression model included only CYP2R1 rs10741657 and CYP27B1 rs3782130, adjusted for diabetes." (PMID 40237935, 2025). "Cyp27b1, the vitamin D 1α-hydroxylase, expression in the kidney and the plasma 1α,25-dihydroxyvitamin D level were higher after 4 weeks of diabetes, while both were normalized after 13 weeks." (PMID 35524739, 2022). "The reverse effect was observed on Cyp27b1 gene transcription, which, as we have shown, increased significantly in diabetics." (PMID 29552033, 2018). "Cholecalciferol treatment significantly attenuated the harmful effect of diabetes on CYP27B1 and VDR expression in hepatic tissue, which additionally supports the association of these changes with the reduced vitamin D bioavailability." (PMID 29552033, 2018). "The administration of cholecalciferol partially or completely abrogated the effects of diabetes on CYP27B1 and VDR expression in the kidneys." (PMID 29552033, 2018). "RT-qPCR study of isolated bone marrow cells demonstrated that in diabetes mRNA levels of Cyp27b1 and Vdr decreased 3.8-fold (p = 0.0001) and 9.0-fold (p = 0.003), respectively, as compared with the control." (PMID 29552033, 2018). "The initial multivariate logistic regression analysis included the selected SNPs (CYP2R1 rs10741657, CYP27B1 rs4646536, and CYP27B1 rs3782130), adjusted for HBP and diabetes." (PMID 40237935, 2025). "Consistent with the Cyp27b1 mRNA results, the plasma 1α,25(OH)2D level was increased after 4 weeks, while it was not affected after 13 weeks of diabetes." (PMID 35524739, 2022). "Four weeks of STZ-induced diabetes significantly induced Cyp27b1 in the kidney compared to the nondiabetic mice." (PMID 35524739, 2022). "The STZ-induced diabetes increased the Cyp27b1 expression in the kidney after 4 weeks, while there was no longer an effect after 13 weeks." (PMID 35524739, 2022). "Here, the overexpression of VDR and CYP27B1 induced by M. tuberculosis infection was not affected by high glucose concentrations, suggesting a possibility for vitamin D supplementation in patients with diabetes mellitus and TB." (PMID 35204769, 2022). "In contrast, after 13 weeks, the diabetes no longer affected Cyp27b1 expression in the kidney." (PMID 35524739, 2022). "In conclusion, our study indicated that alterations in renal Cyp24a1 expression rather than renal Cyp27b1 expression may be the primary cause to decrease in plasma 1,25(OH)2D levels in rats with STZ-induced diabetes." (PMID 32001956, 2020). "Therefore, our aim was to investigate how T1D changes tissue distribution of CYP27B1 and VDR and whether vitamin D3 (cholecalciferol) treatment can affect diabetes-related dysfunction of the vitamin D-endo/para/autocrine system." (PMID 29552033, 2018).
ovarian carcinoma (13 papers, 2013 to 2025). A malignant neoplasm originating from the surface ovarian epithelium. "Another study showed that decreased CYP27B1 was associated with a more aggressive phonotype for ovarian cancer." (PMID 30157901, 2018). "CYP27B1, vital for steroid biosynthesis, curbs ovarian cancer cell proliferation, migration, and invasion." (PMID 40108724, 2025). "On the contrary, CYP27B1 inhibited the proliferation, invasion, and migration of ovarian cancer cells in vitro." (PMID 35127477, 2021). "A previous study also suggested that CYP27B1 can regulate the behavior of ovarian cancer cells and induce a less aggressive phenotype by affecting the concentration of active vitamin D within the tumor microenvironment." (PMID 33163485, 2020). "After silencing CYP27B1 with siRNA, the proliferation, migration, and invasion of ovarian cancer cells were significantly suppressed, indicating that the function of EZH2 in promoting ovarian cancer progression was achieved by the inhibition of CYP27B1." (PMID 33163485, 2020). "In the present study, the IHC results for the 160 ovarian cancer samples revealed an inverse correlation between the expression levels of EZH2 and CYP27B1, which was significantly associated with the prognosis of ovarian cancer." (PMID 33163485, 2020). "The results showed that steroid biosynthesis was activated after EZH2 knockout in ovarian cancer cells and that the hub gene of steroid biosynthesis, CYP27B1, was upregulated." (PMID 33163485, 2020). "The in vitro experiment demonstrated that CYP27B1 can suppress the proliferation, migration, and invasion of ovarian cancer cells." (PMID 33163485, 2020). "It has been reported that CYP27A1 and CYP27B1 were overexpressed in ovarian cancer cells, which can result in an increase in localized 1,25(OH)2D3 concentrations in the tumor and promote anticancer activity." (PMID 30157901, 2018). "The ovarian cancers showing CYP27B1 expression demonstrated significantly higher lymphocytic infiltration." (PMID 25501638, 2015). "Since calcitriol indicates anticancer activities and CYP27B1 expression can be deregulated during malignant progression, we analyzed its expression in ovarian cancers in relation to pathomorphological features of tumors and overall survival (OS)." (PMID 25501638, 2015). "Normal ovarian epithelium showed the highest levels CYP27B1 with a significant decrease in its expression in ovarian cancers." (PMID 25501638, 2015). "Since we previously found a correlation between expression of CYP27B1 and tumor behavior and clinical outcome in skin melanomas, we analyzed the expression of CYP27B1 in ovarian cancers." (PMID 25501638, 2015). "The expression of CYP27B1 was observed in 80.3% of primary ovarian cancers and in 94.6% of metastases." (PMID 25501638, 2015). "Above all, the rescue experiments demonstrated that the function of EZH2 in ovarian cancer might be dependent on the expression of CYP27B1." (PMID 33163485, 2020). "Our previous study showed reduced CYP27B1 levels in primary and metastatic ovarian cancers compared normal controls, with the strongest reduction found in cancers showing a high proliferation index, lack of immune response, presence of necrosis, and dynamic tumor growth." (PMID 33227893, 2020). "There is a shortage of information regarding CYP27B1 in ovarian cancers." (PMID 25501638, 2015). "In summary, we demonstrated a decrease in CYP27B1 expression in ovarian cancers." (PMID 25501638, 2015). "Our results indicate that local activation of vitamin D3 by the CYP27B1 enzyme in ovarian cancers affects tumor biology, and lack of CYP27B1 appears to be associated with a more aggressive phenotype of the tumor." (PMID 25501638, 2015). "Moreover, CYP27B1, the steroid biosynthesis hub gene, might be a novel therapeutic target for ovarian cancer." (PMID 33163485, 2020). "Moreover, CYP27B1, the hub gene of steroid biosynthesis, might be a novel therapeutic target for ovarian cancer." (PMID 33163485, 2020).
ovarian carcinoma (continued). "Finally, decreased expression of CYP27B1, which hydroxylates 25-hydroxyvitamin D3 into biologically active 1,25-dihydroxyvitamin D3 (calcitriol) correlates with the increased pro-metastatic potential of ovarian cancer cells." (PMID 27091127, 2016). "In the present study, our data showed that CYP27B1 was upregulated after the knockout of the oncogene EZH2, which may reduce the level of H3K27me3 in ovarian cancer cells; this finding was also consistent with previous data." (PMID 33163485, 2020).
colorectal cancer (12 papers, 2010 to 2024). A primary or metastatic malignant neoplasm that affects the colon or rectum. "In contrast, no statistical association was found between the methylation status of VDR, CYP24A1, and CYP27B1 at all CpG sites and the risk of colorectal cancer." (PMID 37644572, 2023). "Conversely, in contrast to our study, in Chinese population, CYP27B1 rs4646536 CC genotype reduced the risk of colorectal cancer compared with the TT genotype." (PMID 33058307, 2021). "Here, we focused on rs10877012 polymorphism in the CYP27B1 gene, with reference to susceptibility for the development of colorectal cancer." (PMID 32260235, 2020). "A compromised vitamin D status, characterized by low serum levels of 25-(OH)D, may increase the risk of colorectal cancer due to limited availability of 25-(OH)D as substrate for the colonic CYP27B1-encoded 25-hydroxyvitamin D-1α-hydroxylase." (PMID 24213465, 2012). "Furthermore, it is important to consider that CYP27B1 -1260 TT was associated with increased colorectal cancer risk; the CYP27B1 gene encodes a member of the CYP monooxygenases family (the 1α-hydroxylase enzyme), localized to the inner mitochondrial membrane of renal cells." (PMID 34959633, 2021). "Nevertheless, COX-2, CYP27B1, and CYP24A1 expressions have also been associated with the pathogenesis of human colorectal cancer linked to chronic inflammation." (PMID 38355711, 2024). "In this context, we conducted this study to examine the association between methylation levels of four vitamin D metabolic pathway-related genes (VDR, CYP24A1, CYP27B1 and CYP2R1) from blood and the risk of colorectal cancer." (PMID 37644572, 2023). "More studies are needed to explore the relationship between the methylation level of CYP27B1 and colorectal cancer and its mechanism." (PMID 37644572, 2023). "The main reason was that CYP27B1 expression was induced in these extrarenal cells like colorectal carcinoma cells." (PMID 36776613, 2023). "The results indicated 2.3 and 2.7 upregulation of CYP2R1 and CYP27B1 genes in colorectal cancer tissues compared to the adjacent tissues, respectively." (PMID 33058307, 2021). "By using quantitative real‐time polymerase chain reaction (qRT‐PCR), we analyzed the expression ratio of CYP2R1, CYP27A1 and CYP27B1 genes within the vitamin D metabolic pathway in a total of 75 colorectal cancer (CRC) tissues compared to the adjacent tissues." (PMID 33058307, 2021). "In comparison with our results, dysregulated expression of CYP2R1 and CYP27B1 genes had been shown in different types of cancer, including oral squamous cell carcinomas and colorectal cancer." (PMID 33058307, 2021). "Overall, the results indicated that 2.3 and 2.7 upregulation of CYP2R1 and CYP27B1 genes in colorectal cancer tissues compared to the adjacent tissues, respectively." (PMID 33058307, 2021). "In similar studies of colorectal cancer patients, expression and activity of CYP27B1 in cancer cells were found lower than in normal cells." (PMID 32847594, 2020). "We hypothesized that the methylation level of CYP24A1 could be negatively associated with colorectal cancer risk, while the methylation levels of VDR, CYP2R1 and CYP27B1 could be positively associated with colorectal cancer risk." (PMID 37644572, 2023). "In this study, we show for the first time that TNFα significantly reduced CYP27B1 mRNA expression and expression of the calcium ion channel TRPV6 in colorectal cancer cells." (PMID 24120915, 2014).